S100A8 (S100 calcium binding protein A8)
Diseases named in the same sentence as S100A8 in open-access papers (continued):
Sharing a sentence is not in itself a finding about the gene and the disease.
epidermodysplasia verruciformis (3 papers, 2018 to 2021). A rare inherited genodermatosis characterized by chronic infection with human papillomavirus (HPV) leading to polymorphous cutaneous lesions and high risk of developing non melanoma skin cancer. "This expression profile was also observed in a previous study, when S100A8 and S100A9 protein expression in the skin of epidermodysplasia verruciformis (EV) patients was investigated." (PMID 30567500, 2018).
fungal infections (3 papers, 2013 to 2023). "Although invasive fungal infections are not commonly associated with influenza infections, the expression of proteins such as S100A8, S100A9 may also exert antifungal effects." (PMID 23467809, 2013).
influenza (3 papers, 2013 to 2024). An acute viral infection of the respiratory tract, occurring in isolated cases, in epidemics, or in pandemics; it is caused by serologically different strains of viruses (influenzaviruses) designated A, B, and C, has a 3-day incubation period, and usually lasts for 3 to 10 days. "Previous research has shown that inflammation-related factors (IL-1, TNF, CXCL1, CXCL2, S100A8, and S100A9) predominantly express in neutrophils, and neutrophils infiltration largely account for lethal influenza infection." (PMID 35495713, 2022). "Incubation of influenza-infected BALF with neutrophils did not significantly alter the gene expression of cathelicidin, S100A8, S100A9, lactotransferrin, pentraxin-3, and MMP9 (data not shown)." (PMID 23467809, 2013).
interstitial lung disease (3 papers, 2020 to 2024). A diverse group of lung diseases that affect the lung parenchyma. "Of note, SAA1 and S100A8 were associated with interstitial lung disease in patients with DM in a previous study." (PMID 38396646, 2024). "Plasma S100A8 levels were increased in diffuse cutaneous SSc (dcSSc) and might serve as a possible biomarker for interstitial lung disease (ILD)." (PMID 32679721, 2020).
intestinal tumor (3 papers, 2017 to 2024). "Firstly, because of the lack of primary intestinal tumor cells or intestinal tumor organoids derived from patients, we were unable to directly detect the killing activity of Sec C and the function of S100A8 in a simulated human physiological environment." (PMID 38607060, 2024).
keratitis (3 papers, 2016 to 2023). A corneal disease that is characterized by inflammation of the cornea. "In a paper on P. aeruginosa-induced keratitis, the authors discuss the role of S100A8/A9 in the host defense towards P. aeruginosa infections in vivo, as the genes for S100A8/A9 seem to be the most highly upregulated by bacterial flagellin exposure." (PMID 32664205, 2020). "Our findings suggest that S100A8 is involved in the pathological inflammation of EIU and keratitis, and that measuring S100A8 levels can be a useful method to monitor inflammatory activity in AAU." (PMID 27786310, 2016). "We identified several genes and pathways involved in the host response to infectious keratitis, including CXCL9, CXCR3, and MMP9 for viral, and S100A8/A9, MMP9, and the IL17 pathway for bacterial/fungal keratitis." (PMID 38274739, 2023). "We identified several specific genes and pathways involved in the host response to infectious keratitis, including CXCL9, CXCR3, and MMP9 for viral, and S100A8/A9, MMP9, and the IL17 pathway for bacterial/fungal keratitis." (PMID 38274739, 2023). "Here, we determined the role of S100A8-positive cells in acute anterior uveitis (AAU) and keratitis." (PMID 27786310, 2016). "It is likely that S100A8-positive granulocytes and monocytes/macrophages may play a role in the late phase of EIU and keratitis." (PMID 27786310, 2016).
keratoconus (3 papers, 2020 to 2025). A degenerative, structural disorder of the eye, characterized by a cone-shaped protrusion of the cornea. "Our study further confirmed that feature genes such as the S100A8/A9 complex, KRT14, and KRT15 were significantly associated with the increased risk of keratoconus, and alterations in these genes were closely related to corneal structural stability, mechanical strength, and disease progression." (PMID 40426861, 2025). "In addition, a combination of genes significantly upregulated in the KJ samples only, S100A8, S100A9, ADAMTS14, LYPD2 and AOC1 may yield distinguishing biomarkers for subtypes of keratoconus." (PMID 32555404, 2020).
kidney cancer (3 papers, 2015 to 2017). Primary or metastatic malignant neoplasm involving the kidney. "Therefore, future studies are required to further elucidate the molecular mechanisms underlying S100A8/A9-mediated carcinogenesis and metastasis of kidney cancer." (PMID 25673070, 2015). "Given that S100A8 acts as an upstream target of EGFR signaling, anti-EGFR therapies, including midostaurin, enzastaurin and gefitinib has been proposed as potential therapy for kidney cancer cells which overexpressed S100A8." (PMID 28183295, 2017). "Expression of S100A8 and EGFR in kidney cancer among Saudi patients (CEGMR dataset) and GEO dataset (GSE781, GSE6344 and GSE7023)." (PMID 25789858, 2015). "Involvement of proinflammatory S100A8 in tumor cell differentiation and progression is largely unclear and not studied in kidney cancer (KC)." (PMID 25789858, 2015).
kidney injury (3 papers, 2022 to 2023). Trauma to the kidney. "In the mouse model, targeting this subgroup to block S100a8/a9 signaling can effectively prevent acute kidney injury caused by ischemia-reperfusion." (PMID 38288129, 2023). "Since S100A8/A9 can activate different receptors, such as TLR4, to promote leukocyte recruitment and secretion of proinflammatory cytokines, such as IL-6 and TNF-α, leading to kidney injury." (PMID 37547329, 2023).
leishmaniasis (3 papers, 2014 to 2024). Infectious disease that is transmitted through the bite of hematophagous female phlebotomine sand flies. "Furthermore, S100A8/S100A9 can act as a very early and sensitive biomarker in experimental leishmaniasis for phagocyte activation linked to an effective Th1-response." (PMID 25098555, 2014). "In the context of leishmaniasis, SNHG29, a member of the SNHG family, was determined as hub lncRNA targeting S100A8 mRNA in L. braziliensis skin infection." (PMID 39639867, 2024).
liver disease (3 papers, 2025). "Alcohol-associated liver disease in mice is generally milder than the severely inflamed liver seen in human sAH, and this may not induce the expression of S100A8 in the recruited macrophages." (PMID 40962953, 2025).
myeloproliferative neoplasm (3 papers, 2020 to 2024). A clonal hematopoietic stem cell disorder, characterized by proliferation in the bone marrow of one or more of the myeloid (i.e., granulocytic, erythroid, megakaryocytic, and mast cell) lineages. "In patients with myeloproliferative neoplasms and murine models, the expression of the alarmin complex S100A8/S100A9, a crucial proinflammatory player in MPNs, in MSC mediates the disease progression toward the fibrotic phenotype." (PMID 38314300, 2024). "It is therefore a possibility that both proteins S100A8 and S100A9 might be of particular relevance to hematological malignancies through their critical role in the progression of pre-leukemic states as myelodysplasic syndrome or myeloproliferative neoplasm." (PMID 33801279, 2021). "In lung injuries, S100A8 transduces its signal via TLR4 and is not mediated by RAGE, which sometimes functions as an inhibitory receptor of AKT proliferation signaling in myeloproliferative neoplasms." (PMID 32903598, 2020).
Myocardial fibrosis (3 papers, 2021 to 2025). "As a well-established biomarker of cardiovascular disease, S100A8/A9 exacerbates cardiac injury by promoting inflammation, causing mitochondrial dysfunction, driving myocardial fibrosis, and promoting apoptosis and autophagy." (PMID 39329929, 2024). "S100A8/A9 knockdown has been shown to reduce myocardial fibrosis and inflammation induced by uremic cardiomyopathy (UCM)." (PMID 39329929, 2024). "In summary, this study demonstrated that the conditioned medium of S100A8/A9-pretreated hAMSCs improved cardiac systolic function and decreased myocardial fibrosis after I/R injury." (PMID 34681835, 2021). "This study demonstrated intravenous administration of the conditioned medium of S100A8/A9-pretreated hAMSCs improved left ventricular function and decreased myocardial fibrosis after I/R injury." (PMID 34681835, 2021).
oral squamous cell carcinoma (3 papers, 2011 to 2025). "Expression of S100A9 and S100A8 in brush biopsies was able to differentiate between normal mucosa from premalignant and oral squamous cell carcinoma cells." (PMID 37810966, 2023).
oropharyngeal squamous cell carcinoma (3 papers, 2016 to 2020). "And on the other hand, a high S100A8 expression was found to be a favorable prognostic factor for the survival of oropharyngeal squamous cell carcinoma." (PMID 29868478, 2018). "In oropharyngeal squamous cell carcinoma, S100A12 in addition to S100A8 and S100A9 was downregulated as observed by IHC; simultaneous reduction in both S100A8 and S100A12 expression was associated with worse overall patient survival." (PMID 26883112, 2016). "Moreover, high expression of S100A8 and S100A12 has a positive prognostic impact on oropharyngeal squamous cell carcinoma." (PMID 32211332, 2020).
peritonsillar abscess (3 papers, 2017 to 2021). An abscess that develops in the space surrounding one or both palatine tonsils. "S100A8/A9 (Calprotectin) serves as a biomarker for various inflammatory diseases, such as for peritonsillar abscess (PTA)." (PMID 33627801, 2021). "We have recently shown that S100A8/A9 in combination with characteristic symptoms serves as a biomarker in a peritonsillar abscess." (PMID 34187480, 2021). "We examined serum and saliva of patients with peritonsillitis, acute tonsillitis, peritonsillar abscess, and healthy controls and found significantly increased levels of S100A8/A9 in patients with PTA." (PMID 29180834, 2017). "The elevated levels of S100A8/A9 in the sera and saliva of patients with peritonsillar abscess represent a new application of the well-established biomarker calprotectin." (PMID 29180834, 2017). "Recently we could show increased levels of S100A8/A9 in the saliva and serum of patients suffering from peritonsillar abscess." (PMID 34187480, 2021). "Thus, for improving quality of care, it was the aim of the study to analyze the potential of S100A8/A9 as an objective marker to identify patients with peritonsillar abscess." (PMID 29180834, 2017). "However, the S100A8/A9 level in patients' saliva with peritonsillar abscess was significantly higher than in controls (24590 ± 5850 ng/ml, p = 0.002)." (PMID 29180834, 2017). "Therefore, it was the aim of the present study to analyse the potential of the QBT to quickly determine salivary S100A8/A9 levels during outpatient consultation and to determine its applicability in the diagnosis of peritonsillar abscess by using the PTA score." (PMID 33627801, 2021). "Hence, ascertainment of S100A8/A9 levels in the serum and saliva and application of the new PTA score is a useful diagnostic tool to differentiate between peritonsillar abscess, peritonsillar cellulitis, or acute tonsillitis during urgent outpatient consultation." (PMID 29180834, 2017). "Using a combination of these characteristic symptoms and S100A8/A9 levels, we developed a PTA score as an objective and appropriate tool to differentiate between peritonsillitis and peritonsillar abscess with a sensitivity of 92% and specificity of 93%." (PMID 29180834, 2017). "If S100A8/A9 levels were excluded, a cut-off value of 0.5 for the existence of PTA was determined which is inadequate for differentiation between acute tonsillitis, peritonsillitis, and peritonsillar abscess." (PMID 29180834, 2017).
pneumococcal pneumonia (3 papers, 2010 to 2023). A febrile disease caused by STREPTOCOCCUS PNEUMONIAE. "Here we characterized the role of functional S100A8/A9 deficiency in a model of pneumococcal pneumonia in mice." (PMID 37467233, 2023). "Collectively, S100A8/A9 proteins are important antibacterial effector proteins of the lung and thus indispensable for survival of pneumococcal pneumonia." (PMID 37467233, 2023). "S100A8/A9 levels were higher in lung tissue and bronchoalveolar lavage fluid during pneumococcal pneumonia in mice." (PMID 20976233, 2010). "In addition, migration of granulocytes and macrophages to the alveoli was diminished during pneumococcal pneumonia when mice were treated with S100A8/A9 antibodies." (PMID 20976233, 2010). "Together, S100A8/A9 limits pneumococcal outgrowth in focal pneumonia by chelation of divalent cations, which in turn limits pneumolysin-driven release of neutrophil-derived NE and subsequent NE-dependent degradation of surfactant proteins, thus favoring survival of pneumococcal pneumonia." (PMID 37467233, 2023).
renal cell carcinoma (3 papers, 2015 to 2024). "This notion can be supported by finding of the overexpression of S100A8 and S100A9 by the cancer cells in renal cell carcinoma." (PMID 31582902, 2019). "In order to investigate the two members of the EF-hand Ca2+ binding protein S100 family, S100A8 and S100A9, in renal cell carcinoma (RCC), serum samples were collected from patients with RCC, transitional cell carcinoma in the kidney, benign renal masses and normal controls." (PMID 25673070, 2015).
septic arthritis (3 papers, 2023 to 2025). "Transcriptome sequencing analysis highlights the potential of S100a8/a9 gene expression as a biomarker for predicting septic arthritis development in mice with S. aureus bacteremia, aiding in the development of more efficient treatment strategies." (PMID 41170422, 2025). "It is known that S100A8/A9 expression levels predict the later development of S. aureus septic arthritis." (PMID 39204252, 2024). "Staphylococcus aureus lipoproteins are the most potent bacterial component causing joint inflammation and bone damage in septic arthritis Here, we i.a injected the mouse knees with synthetic lipopeptides (Pam2CSK4 and Pam3CSK4) to observe whether lipopeptides upregulates S100a8/a9." (PMID 37396347, 2023). "Our data suggest that S100a8 and a9 gene expression levels have predictive values for septic arthritis." (PMID 37396347, 2023). "Transcriptome sequencing analysis identified S100a8/a9 genes to be highly expressed in septic arthritis compared to non-septic arthritis at the early course of infection in an Staphylococcus aureus septic arthritis mouse model." (PMID 37396347, 2023). "We also show that S100a8/a9 is highly expressed in the locally infected joints in murine septic arthritis." (PMID 37396347, 2023). "In conclusion, S100a8/a9 gene expression may serve as a potential biomarker to predict septic arthritis, enabling the development of more effective treatment strategies." (PMID 37396347, 2023). "Is high S100a8/a9 gene expression a causative factor or just a biomarker without any biological meaning for septic arthritis?" (PMID 37396347, 2023). "To understand whether S100a8/a9 is upregulated in the affected joints in septic arthritis, we first i.a. infected the mice knee joints with S. aureus Newman WT strain and measured the S100a8/a9 protein levels of mice knee homogenates at different time points." (PMID 37396347, 2023). "Here, from our next-generation studies on animal models of S. aureus-induced septic arthritis, we found that S100a8/a9 gene expression is one of the top candidates that could be used as a biomarker to predict septic arthritis." (PMID 37396347, 2023). "In the current study, our data strongly suggest that S100a8/a9 gene expression might serve as a predictor for septic arthritis." (PMID 37396347, 2023). "Interestingly, the expression level of the S100a8/a9 gene may predict S. aureus-induced septic arthritis in a mouse model, indicating the possibility of using it as a potential biomarker to forecast the evolution of disease and seek more effective therapeutic strategies." (PMID 41170422, 2025). "Our data clearly show that gene expression levels of S100a8/S100a9, rather than protein levels, predict the development of septic arthritis in mice with systemic S. aureus infection." (PMID 37396347, 2023). "In addition, there were significant differences when we analyzed the S100a8/a9 gene expression levels on day 2 in both septic arthritis mice and mice with infection but without septic arthritis." (PMID 37396347, 2023).
steatosis (3 papers, 2022 to 2025). Increased lipid within the cytoplasm of cells. "Further investigation into this possibility will be essential to fully elucidate the molecular mechanisms underlying CD36 downregulation and steatosis attenuation in S100a8-KO mice." (PMID 41178716, 2025). "Loss of S100a8 in macrophages led to a reduction in liver injury and steatosis, as evidenced by lower serum ALT levels and reduced liver weight compared with WT controls." (PMID 41178716, 2025). "Given that PA induces S100A8 expression as revealed by the current study, this finding further supports the clinical relevance of S100A8+ macrophage induction in steatosis." (PMID 41178716, 2025). "Conditional deletion of S100a8 in macrophages reduces steatosis in HFD-fed mice." (PMID 41178716, 2025). "Although we were unable to directly test this notion in patients due to the difficulty of obtaining paired liver and adipose tissues from the same patients, several lines of evidence support a link between adipocyte death and steatosis/MASLD in patients via the activation of S100A8+ macrophages." (PMID 41178716, 2025). "Interestingly, in our study, liver expression of MDSC markers S100A8/S100A9/S100A12 was positively correlated with ATI, a measure of steatosis." (PMID 40257301, 2025). "Adipocyte-specific overexpression of the Bcl2 gene mitigated HFD-induced steatosis and MASLD progression in mice, accompanied by notable alterations in the hepatic infiltration of macrophages, particularly a population of S100A8+ macrophages identified via single-cell RNA-Seq (scRNA-Seq) analysis." (PMID 41178716, 2025).
thyroid cancer (3 papers, 2012 to 2021). "The damage-associated molecular pattern proteins, S100A8 and S100A9, enhanced growth and invasiveness of various cancer cell lines and are implicated in liver, brain, breast, colon, thymus and thyroid cancers." (PMID 34517344, 2021). "In thyroid carcinoma, expression of S100A8 and S100A9 in cancer cells is crucial for dedifferentiation." (PMID 22838504, 2012).
unstable angina pectoris (3 papers, 2017 to 2025). "The expression of S100A8/A9 complex in neutrophils infiltrating atherosclerotic plaques of unstable angina pectoris is elevated, suggesting its involvement in the inflammation of atherosclerotic plaques in patients with unstable angina pectoris." (PMID 37217870, 2023).